TPX2 (TPX2 microtubule nucleation factor)
Diseases named in the same sentence as TPX2 in open-access papers (continued):
Sharing a sentence is not in itself a finding about the gene and the disease.
lung cancer (14 papers, 2011 to 2024). A malignant neoplasm involving the lung. "We conducted experimental validations and explored the biological functions of TPX2 in a lung cancer cell line, providing tangible evidence for our bioinformatics predictions." (PMID 38315450, 2024). "Lastly, we verified TPX2 expression at both mRNA and protein levels in lung cancer tissues as well as explored biological functions in a lung cancer cell line." (PMID 38315450, 2024). "CDC20 together with CENPA, CDK1, AURKA, and TPX2 were also diagnostic biomarkers in LUAD, and elevated mRNA levels of CDC20 were correlated with poor prognosis of lung cancer." (PMID 34650921, 2021). "The clinical significance of TOP2A and probable signaling pathways it involved in were further explored, and a positive correlation between TOP2A and TPX2 expression was found in lung cancer tissues." (PMID 31528121, 2019). "TPX2 overexpression is a biomarker of poor prognosis in brain, breast, colorectal, and lung cancers." (PMID 27626693, 2016). "In lung cancer, an increased TPX2 immunohistochemical labeling index was correlated with the differentiation grade, stage, and lymph node metastasis." (PMID 25914189, 2015). "Preliminary functional studies were performed on lung cancer cells to investigate the role of TPX2." (PMID 38315450, 2024). "The knockdown of TPX2 effectively reduced lung cancer cells proliferation, and invasion." (PMID 38315450, 2024). "We also found that TPX2 promoted the proliferation and migration of lung cancer A549 cells in vitro, suggesting that TPX2 was involved in developing NSCLC and could be a therapeutic target for NSCLC." (PMID 36202977, 2022).
ovarian carcinoma (13 papers, 2008 to 2023). A malignant neoplasm originating from the surface ovarian epithelium. "Expression levels of TPX2 are increased in a variety of cancers and we found that TPX2 gene expression levels are elevated in breast and ovarian cancers with pathogenic BRCA mutations compared to BRCA wild-type cancers." (PMID 36350633, 2022). "Previously, TPX2 was shown to be amplified in a number of genomically unstable cancers, including gastric, colon, oral squamous cell carcinoma, and ovarian cancer." (PMID 30177840, 2019). "There is an overexpression of both AURKA and TPX2 in many different cancer forms, including ovarian cancer, and it has been proposed that TPX2 and AURKA is a functional unit with oncogenic properties." (PMID 23029477, 2012). "TPX2 has an important function in spindle assembly during cell division and has previously been shown to be overexpressed in ovarian cancer, including MD/PD SC, and other malignancies." (PMID 23029477, 2012). "Aurora-A kinase and TPX2, an activator of Aurora-A, are two of the most significantly overexpressed genes in ovarian carcinomas." (PMID 19077237, 2008). "Notably, in separate but parallel investigations conducted by our team, we observed significant vulnerability of the spindle assembly motor proteins KIF11 and KIF15 and their binding partner TPX2 in epithelial ovarian cancer (unpublished data)." (PMID 37894278, 2023). "TPX2 and Aurora-A are genes differentially expressed in ovarian cancer." (PMID 24625450, 2014). "However, multivariate analyses demonstrate a higher risk for patients expressing either RAN or TPX2 than for those expressing XPO7, suggesting a more significant contribution of RAN’s mitotic function to ovarian cancer progression than its nucleo-cytoplasmic function." (PMID 24625450, 2014). "In one network analysis of ovarian cancer, COL5A2, TPX2, and BIRIC5 were also identified as hub genes using the joint sparse regression model." (PMID 28562334, 2017). "Overall, our data validates previously known ovarian cancer genes, such as ERBB2, and also identified novel potential drivers such as MYNN, PUF60 and TPX2." (PMID 20386695, 2010).
endometrial cancer (12 papers, 2008 to 2025). Primary or metastatic malignant neoplasm involving the endometrium (mucous membrane that lines the endometrial cavity). "Validated on tissue samples, TPX2 was shown to be relevant for risk assessment especially in grade 1 and 2 endometrial cancer." (PMID 33546293, 2021). "TPX2 affects the malignant progression of endometrial cancer cells by coupling the CX3CR1/CXCL10 chemokine pathway to the PI3K/Akt signaling pathway." (PMID 40511304, 2025). "Sp1 negatively regulated TPX2 expression, affecting the malignant progression of endometrial cancer cells by coupling the CX3CR1/CXCL10 chemokine pathway to the PI3K/Akt signaling pathway." (PMID 38466034, 2024). "Our findings corroborate previous studies that have implicated TPX2, BUB1, and ESPL1 in the development and progression of endometrial cancer." (PMID 39596419, 2024). "Sp1 regulates TPX2 expression, resulting in a cascade effect, in EC; it affects the malignant progression of endometrial cancer cells by coupling the CX3CR1/CXCL10 chemokine pathway to the PI3K/Akt signaling pathway." (PMID 38466034, 2024). "KIF4A, in the kinesin protein superfamily, is closely related to mitochondrial autophagy; it interacts with TPX2, a protein involved in DNA damage repair in response to replication stress, to inhibit TPX2 ubiquitylation and enhance genomic stability in endometrial cancer cells." (PMID 38711526, 2024).
esophageal cancer (12 papers, 2017 to 2025). A primary or metastatic malignant neoplasm involving the esophagus. "TPX2 represents a novel prognostic factor for esophageal cancer, and he 5‐year overall survival rate of TPX2 high expression group was significantly lower than that of TPX2 low expression group." (PMID 35778922, 2022). "A study of TPX2 in esophageal cancer showed that the 5-year survival rate of esophageal cancer patients with concomitant high TPX2 expression levels was significantly lower than that of esophageal cancer patients with low TPX2 expression levels." (PMID 33912448, 2021).
melanoma (11 papers, 2018 to 2025). A malignant, usually aggressive tumor composed of atypical, neoplastic melanocytes. "In our study, TPX2 was found to be a hypomethylated-upregulated gene in melanoma and associated with the poor prognostic of melanoma patients, which suggested that TPX2 may be used as a novel prognostic marker for the development and progression of SKCM." (PMID 35991567, 2022). "Indeed, TPX2 overexpression has been linked to shorter OS in melanoma patients." (PMID 39766071, 2024). "In the context of cancer regulation, plasma cell-derived exosomes which are derivatives of B cells regulate tumor proliferation by carrying miR-330-3p which downregulates TPX2; a critical gene involved in sustaining melanoma cell proliferation." (PMID 41142789, 2025). "In melanoma cells, a mutation in a key AURKA-inactivating phosphatase results in aberrant AURKA activation and its sustained interaction with TPX2." (PMID 34944109, 2021). "Survival curves showed that high expression of FOXM1,\ EXO1, KIF20A, TPX2, and CDC20 in melanoma patients with 5 of the top 10 hub genes was associated with reduced overall survival (OS)." (PMID 33912448, 2021). "FOXM1, KIF20A, TPX2, CDC20, and EXO1 are hub genes of melanoma prognostic, and their high expression is strongly associated with low prognosis in melanoma patients." (PMID 33912448, 2021). "Additionally, TPX2 is strongly co-expressed with KIF20A, a factor implicated in the development and progression of many cancer types, including melanoma and cervical squamous cell carcinoma." (PMID 40362354, 2025). "It targets TPX2, which negatively regulates TPX2 expression to inhibit melanoma cell proliferation." (PMID 37342327, 2023). "Interestingly, in our study, patients with high TPX2 expression of melanoma had a relatively shorter overall survival than patients with low expression." (PMID 33912448, 2021). "FOXM1, EXO1, KIF20A, TPX2, and CDC20 are prognosis-associated core genes of melanoma, and their high expression correlates with the low prognosis of melanoma patients and can be used as biomarkers for melanoma diagnosis, treatment, and prognosis prediction." (PMID 33912448, 2021). "The protein expression of FOXM1, KIF20A, TPX2, CDC20, and EXO1 was higher in melanoma than in paraneoplastic tissues, consistent with our analysis results." (PMID 33912448, 2021). "In contrast, the vehicle samples of cell line M130227 predominantly upregulate factors that indirectly influence MAPK pathway activity through growth factor signaling and cell cycle progression, thereby promoting melanoma aggressiveness (e.g., PGF, CDCA8, DLGAP5, TPX2)." (PMID 41199020, 2025). "Protocols surrounding down-regulation of TPX2 through BDEs have not been fully optimized and need to be validated, however, they show great potential to inhibit the development of melanoma." (PMID 41142789, 2025). "FOXM1, KIF20A, TPX2, CDC20, and EXO1 could be used as biomarkers for melanoma diagnosis, treatment, and prognosis prediction." (PMID 33912448, 2021). "In conclusion, by combining the WGCNA analysis method with differentially expressed gene analysis, our study identified the genes FOXM1, KIF20A, TPX2, CDC20, and EXO1 highly correlated with survival melanoma patients and have the potential to serve as a prognostic biomarker in melanoma." (PMID 33912448, 2021).
lymph node metastasis (8 papers, 2013 to 2024). "High TPX2 expression was positively associated with age, type of histology, depth of tumor, lymph node metastasis, stage, and remote metastasis or recurrence." (PMID 28069036, 2017). "Cox multivariate regression analysis revealed that deep myometrial invasion, advanced clinical stage, and lymph node metastasis, but not TPX2 expression, were independent risk factors for EC (p < 0.05)." (PMID 38466034, 2024). "The immunohistochemical labeling index of TPX2 was related to the degree of differentiation, stage, and lymph node metastasis of lung squamous cell carcinoma, and the overexpression of TPX2 was significantly correlated with the decrease of 5-year survival rate." (PMID 32626756, 2020).
clear cell renal cell carcinoma (7 papers, 2019 to 2025). "TPX2, a microtubule-associated protein, is overexpressed in metastatic hepatocellular carcinoma and clear cell renal cell carcinoma, underscoring its potential as both a biomarker and therapeutic target in aggressive tumors." (PMID 41244050, 2025).
esophageal squamous cell carcinoma (6 papers, 2014 to 2025). Esophageal squamous cell carcinoma (ESCC) is a type of esophageal carcinoma (EC) that can affect any part of the esophagus, but is usually located in the upper or middle third. "Previous studies showed that in esophageal squamous cell carcinoma, LINC00337 could recruit E2F4 to upregulate TPX2 transcription, form LINC00337/E2F4/TPX2 axis." (PMID 33292231, 2020).
neuroblastoma (6 papers, 2008 to 2024). Neuroblastoma (NB) is the most common solid, extracranial childhood tumor. "Expression of bub1 was found to significantly affect overall survival and event-free survival of patients with neuroblastoma, positively correlate with the expressions of tpx2 and the ASPM gene, and negatively correlate with host immune infiltration." (PMID 36237324, 2022). "For example, in a study of 43 cases of neuroblastoma, TPX2 was found to positively regulate the proliferation, cell cycle, and survival of neuroblastoma cells, which have an oncogenic role in the development of neuroblastoma, indicating the value of TPX2 as a prognostic indicator in neuroblastoma." (PMID 38833082, 2024).
squamous cell lung carcinoma (6 papers, 2008 to 2020). A carcinoma arising from squamous bronchial epithelial cells. "Aberrant expression of TPX2 has been associated with both malignant transformation of respiratory epithelium and progression of squamous cell lung cancer." (PMID 24341487, 2013). "Aberrant expression of TPX2 may be essential in both malignant transformation of respiratory epithelium and progression of squamous cell lung cancer." (PMID 28427189, 2017).
cholangiocarcinoma (5 papers, 2019 to 2023). A carcinoma that arises from the intrahepatic biliary tree (intrahepatic cholangiocarcinoma) or from the junction, or adjacent to the junction, of the right and left hepatic ducts (hilar cholangiocarcinoma). "We sought to confirm the co-expression of TPX2, PLK1 and AURKA in cholangiocarcinoma datasets." (PMID 32127951, 2020). "Notably, both TPX2 and PLK1 were among the top 20 correlated genes with AURKA in the TCGA dataset of cholangiocarcinoma based on Person correlation analysis." (PMID 32127951, 2020).
COVID-19 (5 papers, 2023 to 2025). A disease caused by infection with severe acute respiratory syndrome coronavirus 2. "In COVID-19, TPX2 has been identified as a potential therapeutic target, given its role in regulating cell cycle and stress responses under viral infection." (PMID 40408617, 2025). "PPI network analysis from STRING revealed that as a hub gene, TPX2 may be a novel COVID-19 intervention target and biomarker." (PMID 37007526, 2023). "TPX2 may be a novel COVID-19 intervention target and biomarker." (PMID 39371335, 2024). "Among the ten candidate hub genes, we found that 8 hub genes were differentially upregulated in HBV and COVID-19, so we further narrowed the scope of the study to 8 hub genes, including CDK1, E2F7, E2F8, TYMS, KIF20A, CENPE, TPX2, HMMR." (PMID 40408617, 2025). "TPX2 and KIF11 were upregulated in peripheral blood mononuclear cells and contributed to diagnosing and managing COVID-19 patients." (PMID 36911196, 2023). "In the study of tissue regeneration after acute injury, we analyzed the database of ALF and COVID-19 by bioinformatics method and found common hub genes, including CDC20, CENPF, KIF4, KIF11, NUSAP1, TPX2, and PTTG1, which were related to mitosis and cell cycle regulation." (PMID 36911196, 2023).
non-small cell lung carcinoma (5 papers, 2020 to 2025). A group of at least three distinct histological types of lung cancer, including non-small cell squamous cell carcinoma, adenocarcinoma, and large cell carcinoma. "Furthermore, the upregulation of TPX2 expression has been shown to significantly promote non-small-cell lung cancer, hepatocellular cell migration, and invasion; it has also been associated with increased cell plasticity." (PMID 36304254, 2022). "In PDAC, genomic hybridization and integrated analyses of RNA and DNA identified TPX2 as a potential target for amplification in both PDAC and non-small-cell lung cancer." (PMID 33033514, 2020).
breast tumors (4 papers, 2011 to 2023). "Five of these genes (NEK2, PLK, BIRC5, TPX2 and AURKA) displayed DNA amplification (or polysomy) in more than 30% of breast tumors." (PMID 21352579, 2011). "In addition, 6/7 PC-CIN genes (CEP55, UBE2C, MELK, TPX2, PTTG1, and CDCA3) were also found to be among the top DEGs identified through comparison of high aneuploidy versus low aneuploidy breast tumors in TCGA." (PMID 32380981, 2020).
colorectal adenoma (4 papers, 2017 to 2023). An adenoma that arises from the colon or rectum. "The AURKA and TPX2 genes are also related to carcinogenesis in CRC by promoting the progression of colorectal adenoma to colorectal adenocarcinoma." (PMID 34070979, 2021).
renal carcinoma (4 papers, 2020 to 2025). A carcinoma arising from the epithelium of the renal parenchyma or the renal pelvis. "Given that TPX2 has already been established as a clinically relevant factor in renal cancer, further validation would be particularly valuable for BCL9, which emerges as a potential target for enhancing tumor sensitivity to anti-PD-1/L1 therapy." (PMID 40362354, 2025). "The upregulation of TPX2 levels has been found to promote the proliferation and invasion of renal cancer cells." (PMID 34671679, 2021). "Additionally, further research is needed to investigate the interplay between TPX2 and BCL9 in renal cancer progression, particularly in the context of their role in modulating the tumor immune microenvironment." (PMID 40362354, 2025). "This may be due to the significant upregulation of TPX2 in RCC tissues, thus increasing the proliferation and invasive ability of renal cancer cells." (PMID 32626756, 2020).
lymphoma (3 papers, 2011 to 2019). A malignant (clonal) proliferation of B- lymphocytes or T- lymphocytes which involves the lymph nodes, bone marrow and/or extranodal sites. "Indeed, TPX2 has been associated with various cancers such as breast, lung, prostate, lymphoma and malignant astrocytoma, and has also been correlated with genomic instability." (PMID 24625450, 2014). "Downregulation of tpx2 is associated with abnormal spindle formation with the presence of giant cells and the absence of mitotic figures in histological specimens of lymphoma tissue." (PMID 22312355, 2011).
osteosarcoma (3 papers, 2020 to 2024). A usually aggressive malignant bone-forming mesenchymal neoplasm, predominantly affecting adolescents and young adults. "Furthermore, microRNA prediction revealed that miR-29c-3p regulates TPX2 to induce cell proliferation in osteosarcoma through the AKT signaling pathway." (PMID 38914609, 2024).
pancreatic ductal adenocarcinoma (3 papers, 2023 to 2025). An infiltrating adenocarcinoma that arises from the epithelial cells of the pancreas. "Many of those genes were related to various kinds of neoplasia progression (Tpx2, Id3, Top2a, Dab2, Mecom, Nrp1107–112), including pancreatic ductal adenocarcinoma, or pancreatitis (Gsn113)." (PMID 37689751, 2023). "Additionally, in pancreatic ductal adenocarcinoma (PDAC), high TPX2 levels are associated with diminished efficacy of gemcitabine-based chemotherapy, indicating its potential as a predictive marker for gemcitabine resistance." (PMID 40362354, 2025). "TPX2, a critical target of KRAS, has been reported to be involved in the development of pancreatic ductal adenocarcinoma (PDAC) through the regulation of hypoxia-mediated HIF-1." (PMID 37240068, 2023).
papillary renal cell carcinoma (3 papers, 2020 to 2024). A rare subtype of renal cell carcinoma, arising from the renal tubular epithelium and showing a papillary growth pattern, which typically manifests with hematuria, flank pain, palpable abdominal mass or nonspecific symptoms, such as fatigue, weight loss or fever. "TPX2 is overexpressed in papillary renal cell carcinoma and is related to poor prognosis." (PMID 33154194, 2020). "Therefore, we believe that factors in the TPX2 co-expression module might affect the prognosis of papillary renal cell carcinoma by participating in the process of regulating cell proliferation, and we verified it in function experiment." (PMID 33154194, 2020).
adenoma (2 papers, 2013 to 2018). A neoplasm arising from the epithelium. "Array data mining found that genes such as Ccnb1, Igfbp3, Nusap1, Pttg1, Racgap1, Top2a, Tpx2, which are associated with the aggressive behaviour of various human tumors, including PAs, and proto-oncogenes such as Ect2, Kit, Kras, Lyn, Ret are up-regulated in rat adenomas." (PMID 23756599, 2013).
chronic rhinosinusitis (2 papers, 2020 to 2024). Chronic form of sinusitis. "For example, in the chronic rhinosinusitis mouse model, upregulation of miR-335 reduced inflammation via negative regulation of the TPX2-mediated AKT/GSK3β signaling pathway." (PMID 39305404, 2024). "More recently, hsa-miR-335-5p is shown to reduce inflammation via negative regulation of the TPX2-mediated AKT/GSK3β signaling pathway in a chronic rhinosinusitis mouse model." (PMID 33032623, 2020).
dengue fever (2 papers, 2022 to 2024). "IFI27 and TPX2 have also been highlighted in the context of dengue virus infection by other studies." (PMID 35220956, 2022). "IFI27, TPX2, CDT1 and CDCA3 are particularly known for their role in cancer, and TPX2 also for its role in the context of infectious diseases, in particular dengue fever." (PMID 35220956, 2022).